NR4A2 (nuclear receptor subfamily 4 group A member 2)
Description:
Transcriptional regulator which is important for the differentiation and maintenance of meso-diencephalic dopaminergic (mdDA) neurons during development. It is crucial for expression of a set of genes such as SLC6A3, SLC18A2, TH and DRD2 which are essential for development of mdDA neurons (By similarity).
Synonyms: NOT; NURR1; TINUR; RNR1; HZF-3; IDLDP
Tractability: Small molecule: a structure with a bound ligand is known; a high-quality ligand is known; it has a binding pocket of medium quality; it belongs to a druggable protein family. PROTAC: ubiquitination databases record sites on it; a small molecule that binds it is known.
Target class: Transcription factor; Nuclear hormone receptor subfamily 4; Nuclear receptor; Nuclear hormone receptor subfamily 4 group A; Nuclear hormone receptor subfamily 4 group A member 2
Gene: Protein-coding gene on chromosome 2 (156,324,432 to 156,342,348, reverse strand). Ensembl gene ENSG00000153234.
Subcellular location: Cytoplasm; Nucleus
Subcellular location (Human Protein Atlas): Nuclear speckles
Pathways (Reactome):
Gene expression (Transcription): Nuclear Receptor transcription pathway
Metabolism of proteins: SUMOylation of intracellular receptors
Gene Ontology:
Molecular function: protein binding; sequence-specific double-stranded DNA binding; beta-catenin binding; DNA binding; DNA-binding transcription activator activity, RNA polymerase II-specific; DNA-binding transcription factor activity, RNA polymerase II-specific; nuclear glucocorticoid receptor binding; nuclear receptor activity; nuclear retinoid X receptor binding; protein heterodimerization activity; RNA polymerase II cis-regulatory region sequence-specific DNA binding; DNA-binding transcription factor activity; RNA polymerase II transcription regulatory region sequence-specific DNA binding; sequence-specific DNA binding; zinc ion binding
Biological process: DNA-templated transcription; negative regulation of apoptotic signaling pathway; negative regulation of transcription by RNA polymerase II; canonical Wnt signaling pathway; cellular response to corticotropin-releasing hormone stimulus; central nervous system neuron differentiation; dopaminergic neuron differentiation; fat cell differentiation; midbrain dopaminergic neuron differentiation; neuron migration; positive regulation of transcription by RNA polymerase II; regulation of transcription by RNA polymerase II; intracellular receptor signaling pathway; regulation of DNA-templated transcription
Cellular component: cytoplasm; nuclear speck; nucleus; chromatin; nucleoplasm; protein-containing complex; transcription regulator complex
Genetic constraint (gnomAD): Loss-of-function variants: 1 observed, 50.9 expected, observed/expected ratio (o/e) 0.0196, 90% interval 0.006 to 0.093. The upper end of that interval is the gene's LOEUF score, 0.093, which puts it in group 1 of 6, group 1 being the genes least tolerant of losing a copy. Missense variants: 613 observed, 790.52 expected, observed/expected ratio (o/e) 0.78, 90% interval 0.73 to 0.83. Synonymous variants: 328 observed, 320.17 expected, observed/expected ratio (o/e) 1.02, 90% interval 0.94 to 1.12.
Gene-disease validity (ClinGen):
ClinGen rates the evidence that NR4A2 causes each of these diseases.
complex neurodevelopmental disorder (autosomal dominant): Definitive. A disorder that involves more than one phenotype associated with the central nervous system, including but not limited to intellectual disability, autism, and seizures (epilepsy).
Homologues: Orthologues: chimpanzee NR4A2 (100% identical), guinea pig NR4A2 (100% identical), rabbit NR4A2 (100% identical), dog NR4A2 (99% identical), macaque NR4A2 (99% identical), pig NR4A2 (99% identical), mouse Nr4a2 (99% identical), tropical clawed frog nr4a2 (91% identical), rat Nr4a2 (90% identical), zebrafish nr4a2a (87% identical), Drosophila melanogaster Hr38 (50% identical), Caenorhabditis elegans nhr-6 (27% identical). Paralogues in human: NR4A3 (60% identical), NR4A1 (55% identical).
Diseases named in the same sentence as NR4A2 in open-access papers:
NR4A2 is named in the same sentence as 238 diseases in open-access papers, as found by Europe PMC text mining. Sharing a sentence is not in itself a finding about the gene and the disease. The quoted sentences say what the papers report.
Parkinson disease (107 papers, 2008 to 2026). A progressive degenerative disorder of the central nervous system characterized by loss of dopamine producing neurons in the substantia nigra and the presence of Lewy bodies in the substantia nigra and locus coeruleus. "Eight loci-PRKN, SNCA, GBA1, LRRK2, APOE, MTHFR, SYT11, and NR4A2-emerged as recurrently associated with Parkinson's disease." (PMID 41798285, 2026). "Dysfunction of the NR4A2 gene has been linked to a wide range of disorders associated with dopaminergic impairment, encompassing Parkinson’s disease (PD), schizophrenia, and manic depression." (PMID 41019763, 2025). "In particular, NR4A2 has been implicated in Alzheimer’s disease (AD) progression, Parkinson disease, schizophrenia, substance abuse (alcohol and cocaine), neurodevelopmental disorders and cognitive impairment among others." (PMID 41009723, 2025). "Since NR4A2 plays a role in maintenance of adult midbrain dopaminergic neuron, it is also associated with neurodegenerative diseases, such as Parkinson’s or Alzheimer’s disease, schizophrenia, and manic depression." (PMID 41019763, 2025). "NR4A2 alterations have been linked to DA-associated brain disorders such as Parkinson’s disease and schizophrenia." (PMID 37957291, 2024). "Lower expression of NR4A2 caused impaired development and differentiation of midbrain neurons that promoted DA neurodegeneration and neuroinflammation, hallmark parkinsonism." (PMID 34066949, 2021). "It is imperative to correctly understand the functional brain organization patterns of this gene, as mutations of human NR4A2 have been linked to schizophrenia, Parkinson's Disease, and neuroprotection for Alzheimer's Disease." (PMID 33855704, 2021). "The NR4A2 gene plays a role in dopamine regulation, and has been implicated in depression, drug addiction, Parkinson’s disease, schizophrenia and bipolar disorder." (PMID 34233707, 2021). "NR4A2 has been implicated in drug addiction, Parkinson’s disease, schizophrenia and bipolar disorder." (PMID 31827426, 2019). "Furthermore, NR4A2 genetic variants have been implicated as a risk factor for several neurological and psychiatric disorders, including Parkinson’s disease, depression, schizophrenia and substance abuse." (PMID 41009723, 2025). "Similarly, genetic variants associated with familial Parkinson’s disease have been identified to reduce NR4A2 gene expression." (PMID 41009723, 2025). "A loss of function of the NR4A2 gene is associated with Parkinson’s disease." (PMID 39202342, 2024). "Among the regulatory factors involved, NR4A2 has already been reported to harbor rare mutations in familial PD and its pharmacological activation confers neuroprotective effects in toxin-induced models of Parkinsonism." (PMID 36681675, 2023). "In human pathology, earlier studies have indicated NR4A2 may be a potential susceptibility gene for Parkinson’s disease and schizophrenia by case-control association studies." (PMID 35992907, 2022). "Moreover, we noticed the presence of the nuclear receptor NR4A2, a TF encoded by a gene harboring genetic variants that have been associated with familial Parkinson’s disease susceptibility." (PMID 34490253, 2021). "NR4A2 mutations are strongly linked to familial Parkinson’s disease." (PMID 34445083, 2021). "Nr4a2 (Nurr1) plays an essential role as a neuroprotector, and mutations in this gene or its absence are associated with dysfunction in neuronal development and chronic pathologies like Parkinson’s disease." (PMID 34048439, 2021). "The role of NR4A2 and effects of NR4A2 ligands on different aspects of neuronal toxicities including learning and memory and Parkinson’s disease have been extensively investigated whereas this is not the case for NR4A1 ligands." (PMID 40871737, 2025). "NURR1 (NR4A2) serves as a critical regulatory factor in both neuroblastoma progression and Parkinson’s disease." (PMID 40926269, 2025).
Parkinson disease (continued). "NR4A2 protein agonists have been shown to reverse behavioral and histological abnormalities in animal models of Parkinson’s." (PMID 38791237, 2024). "NR4A2 is involved in autoimmune and neurodegenerative diseases, especially in Parkinson’s disease, where the reduced expression of this gene in peripheral blood can be considered as a potential biomarker for diagnosis, and a promising approach to therapy." (PMID 35163587, 2022). "Our findings confirmed that NR4A2 haploinsufficiency was responsible for certain clinical features in patients and proposed the potential appearance of dystonia and/or parkinsonism related to NR4A2 which should be attached importance to in the follow-ups." (PMID 35992907, 2022). "Between five and 10 patients had juvenile neuronal ceroid lipofuscinosis (JNCL), PTRHD1, RAB39B, X‐linked parkinsonism with spasticity, Alexander disease, dopa‐responsive dystonia‐parkinsonism (NR4A2), Fragile‐X syndrome or spastic paraplegia type 15 (SPG15)." (PMID 36699000, 2022). "The G insertion at IVS6 + 18 of NR4A2 was observed with higher frequency in Parkinson’s patients than in healthy individuals." (PMID 35992907, 2022). "Nurr1 (NR4A2), an orphan nuclear receptor, has been shown to provide significant neuroprotection via inhibition of pro-inflammatory cytokines in Parkinson’s disease, ICH, and acute cerebral ischemic/reperfusion." (PMID 33468172, 2021). "Parkinson’s disease (PD), which results from the degeneration of midbrain dopaminergic neurons, was the first brain pathology that was related to Nr4a2." (PMID 34880728, 2021). "The orphan nuclear receptor Nurr1 (also known as NR4A2) is critical for the development and maintenance of midbrain dopaminergic neurons, and is associated with Parkinson's disease." (PMID 30515963, 2019). "Nurr1 (NR4A2) is a member of the nuclear receptor 4 family of orphan nuclear receptors, and has been studied extensively in Parkinson’s disease recently." (PMID 29209166, 2017). "For example, by searching mouseNET with a set of genes (Mapt, Sncaip, Tbp, Drd4, Ndufv2 and Nr4a2) already known to be involved in Parkinson's disease, we are able to extract other genes annotated to this disease and some novel candidates." (PMID 18818725, 2008). "Furthermore, Nr4a2 protein agonists have been shown to reverse behavioral and histological abnormalities in animal models of Parkinson’s." (PMID 38791237, 2024). "In addition, four genes associated with neurological disorders were significantly upregulated in hydrogel-cultured cells (NR4A2, Parkinson’s disease; A2M & HMOX1, Alzheimer’s; COL21A1, atypical psychosis)." (PMID 28097054, 2017). "Furthermore, exploration of the molecular mechanisms underlying NR4A2-associated intellectual developmental disorder with language impairment and early-onset DOPA-responsive dystonia-parkinsonism is imperative for the development of efficacious therapies and enhanced clinical outcomes." (PMID 41019763, 2025). "Even in absence of genetic variants in the NR4A2 gene directly implied as the cause of Parkinson’s or Alzheimer’s disease, there is strong evidence for the importance of a putative pharmacological modulation of this gene to revert or ameliorate the symptoms in these highly prevalent diseases." (PMID 38791237, 2024). "The neuroprotective transcription factor nuclear receptor related 1 (Nurr1, NR4A2) is in the focus of biomedical research for its promising neuroprotective role in Parkinson’s disease, Alzheimer’s disease, and multiple sclerosis." (PMID 40399628, 2025). "The potential endogenous functions of PGE1 and PGE2 have recently been reported; both compounds bind NR4A2, inhibit inflammation in neuronal cells and are neuroprotective in the MPTP-induced Parkinson’s Disease mouse model." (PMID 38116863, 2024).
Parkinson disease (continued). "NR4A2 missense variants considered to cause NDD occurred in DBD and LBD regions, while others occurring in N-terminal domain (c.289A > G, c.308A > G and c.374C > G) tend to be associated with susceptibility of Parkinson’s disease or schizophrenia, in which a different mechanism might play a role." (PMID 35992907, 2022). "Parkinson's and Huntington's disease were both enriched by APOC1, NUSAP1, NR4A2, ADRB2 and ZNF331." (PMID 39098992, 2024). "For example, in a mouse model of Parkinson’s disease, delivery of an adenovirus construct by CRISPR-SAM via injection into the brain resulted in successful reprogramming of astrocytes into functional neurons through the activation of differentiation factors Ascl1, Lmx1a, and Nr4a2." (PMID 40650152, 2025). "In-depth phenotypic characterization, detailed treatment protocols, and a comprehensive review of published NR4A2 cases offer a thorough understanding of patients afflicted with intellectual developmental disorder with language impairment and early-onset DOPA-responsive dystonia-parkinsonism." (PMID 41019763, 2025).
schizophrenia (34 papers, 2008 to 2025). A major psychotic disorder characterized by abnormalities in the perception or expression of reality. "The level of NR4A2 gene expression is significantly associated with age-dependent neurodegeneration and cognitive function in animal models of PD, schizophrenia (SZ), AD, and attention deficit disorder." (PMID 41009723, 2025). "The association between the NR4A2 gene and cognitive deficit in schizophrenia has been previously reported in a Caucasian population." (PMID 33563249, 2021). "In conclusion, we identified in this study a significant effect of the relationship of the rs34884856 promoter variant and the expression levels of the NR4A2 gene on working memory endophenotypes in schizophrenia patients." (PMID 33563249, 2021). "Different genes involved in the neurodevelopment of dopaminergic neurons can be considered candidate susceptibility genes for schizophrenia and cognitive deficits, for instance, the gene that codes for the nuclear receptor subfamily 4, group A (NR4A2)." (PMID 33563249, 2021). "The current study included 187 schizophrenia patients and 227 controls genotyped for two of the most studied NR4A2 genetic variants in neurological and neuropsychiatric diseases." (PMID 33563249, 2021). "In the present study, an association between the rs34884856 promoter variant of the NR4A2 gene and auditory working memory in schizophrenia patients was identified." (PMID 33563249, 2021). "In this sense, the NR4A2 gene has been implicated in schizophrenia and cognition in different animal models and clinical trials." (PMID 33563249, 2021). "Altogether, these findings indicate that Nr4a2-deficient mice display some phenotypic characteristics of schizophrenia-like dysfunction." (PMID 34880728, 2021). "Our main result was the association of performance on the BDS with the rs34884856 promoter variant and the expression levels of the NR4A2 gene in schizophrenia patients." (PMID 33563249, 2021). "These molecular changes may be associated with different neurotransmitters and neural circuits that are linked to cognitive deficits observed in schizophrenia, many of which are related to NR4A2 gene expression." (PMID 41009723, 2025). "Therefore, we investigate the association between the NR4A2 gene with working memory deficit in schizophrenia in the Mexican population, which is under-represented in human genomic research." (PMID 33563249, 2021). "Our findings suggest that decreased NR4A2 gene expression could be associated with a deficit in auditory working memory in schizophrenia patients depending on their genotype in a sample from a Mexican population." (PMID 33563249, 2021). "Our finding suggested that changes in expression levels of the NR4A2 gene could be associated with working memory in schizophrenia depending on patients’ genotype in a sample from a Mexican population." (PMID 33563249, 2021). "We hypothesized that the NR4A2 gene is associated with working memory performance in schizophrenia in a sample Mexican population." (PMID 33563249, 2021). "Notably, NR4A2 has been extensively studied for its involvement in the development and maintenance of dopaminergic neurons and its association with PD and schizophrenia." (PMID 39435657, 2024). "However, the relationship of NR4A2 expression in PBMC with gene variants in schizophrenia remains unclear." (PMID 33563249, 2021). "Therefore, this study aimed to analyze the genotype effect of two genetic variants (rs34884856 promoter variant and rs35479735 intronic 6 variant), and the expression levels of the NR4A2 and their interactions on performance of working memory ability in schizophrenia." (PMID 33563249, 2021). "We hypothesized that the NR4A2 gene is associated with working memory performance in schizophrenia." (PMID 33563249, 2021). "In schizophrenia (SZ) patients, NR4A2 expression in the dorsolateral prefrontal cortex (DLPFC) was found to be reduced in postmortem samples." (PMID 41009723, 2025).